CP (ceruloplasmin)
Diseases named in the same sentence as CP in open-access papers (continued):
Sharing a sentence is not in itself a finding about the gene and the disease.
colitis (6 papers, 2017 to 2025). Inflammation of the colon. "It was found that SPH treatment decreased the DAI score and colon tissue injury when compared to the colitis-only and CP groups." (PMID 36139127, 2022). "Genetically modified murine models of experimental colitis show that CP plays a role in reducing bowel inflammation." (PMID 33917627, 2021). "In keeping with its antioxidant properties, macrophage-derived ceruloplasmin contributes importantly to protection against inflammation and tissue injury in acute and chronic experimental colitis." (PMID 28450461, 2017). "Treatment with the control TLR-i peptide lacking the cell-penetrating conjugate or the CP peptide alone did not affect the colitis symptoms, which include body weight loss, diarrhea, rectal bleeding, and reduced colon length." (PMID 37215126, 2023). "Colitis was induced with intra-rectal TNBS (2.5 mg/rat), and CP was administered orally (200 mg/kg/day) for 16 days." (PMID 41010469, 2025). "Mice were randomly assigned to four groups: Control (no colitis), Colitis, Colitis/CP (with control peptide treatment), and Colitis/SPH (with SPH treatment)." (PMID 36139127, 2022).
diabetic nephropathy (6 papers, 2012 to 2025). "However, continuing the debate on oxidative stress, in contrast to other studies, a Korean study on diabetic nephropathy found that higher ceruloplasmin levels were associated with faster progression of nephropathy." (PMID 33680612, 2021). "Differing from albumin in terms of their molecular radii and isoelectric points, urinary ceruloplasmin and TF have been shown to predict the onset of microalbuminuria in diabetic nephropathy." (PMID 27590021, 2017). "Ceruloplasmin is a promising marker of diabetic nephropathy, but further studies are necessary to characterize its value compared to UAE, especially in type 1 diabetics, since all the studies have been done in type 2 diabetics." (PMID 22645683, 2012). "It has been reported that urine ceruloplasmin/creatinine ratio has a sensitivity of 90-91%, specificity of 61–66% and 75% concordance, in diagnosing diabetic nephropathy." (PMID 22645683, 2012). "Ito further pointed out that increased urinary copper excretion in patients with advanced diabetic nephropathy may be due to the copper-albumin and ceruloplasmin-copper complexes through the impaired glomeruli." (PMID 36562035, 2022). "The same study also found a similar trend in diabetic nephropathy and neuropathy wherein there was no significant positive trend in serum ceruloplasmin levels with the severity of the diabetic complication." (PMID 33680612, 2021). "The ceruloplasmin/creatinine ratio is higher in diabetic nephropathy compared to nondiabetic nephropathy patients." (PMID 22645683, 2012).
hemochromatosis (6 papers, 2011 to 2025). A disorder of iron metabolism characterized by a triad of HEMOSIDEROSIS; LIVER CIRRHOSIS; and DIABETES MELLITUS. "When iron is abundant, such as in hemochromatosis, ceruloplasmin levels are low and associated with copper deficiency, which may be of importance for certain groups of patients receiving iron treatment." (PMID 36840264, 2023).
leukemia (6 papers, 2014 to 2024). A malignant (clonal) hematologic disorder, involving hematopoietic stem cells and characterized by the presence of primitive or atypical myeloid or lymphoid cells in the bone marrow and the blood. "The IXA cP inhibition profile in leukemia cells confirms earlier studies’ results in MM cell lines that IXA is a potent inhibitor of β5 activity and, to a lesser extent, β1 activity." (PMID 33802801, 2021). "Other conditions with significantly higher mean serum CP levels included malignant tumor, leukemia, various infectious diseases, mucocutaneous lymph node, hyperthyroidism, and connective tissue diseases." (PMID 29324775, 2018). "Given the high efficacy of CP against B-leukemia phenotype and the bad prognosis of 4;11 translocated B-ALL, we further investigated the mechanism of action and the death pathways activated by CP in RS4;11 and SEM cells." (PMID 24980813, 2014). "We showed that CP had a strong growth inhibitory activity on several leukemia cell lines of different lineage and phenotype and it preferentially killed B-lymphoblastic leukemia cells." (PMID 24980813, 2014). "It is possible that CP sensitizes cancer cells by an overload of ER stress condition able to improve leukemia cell death in a synergistic way." (PMID 24980813, 2014). "CP significantly inhibited leukemia cells growth with a GI50 ranging from 1.2 μM to 23 μM for myeloid phenotypes, between 3.9 μM and 16.7 μM for T-lymphoblastic phenotypes and from 0.9 μM to 4.2 μM for B-lymphoblastic cell lines." (PMID 24980813, 2014). "In this study, we evaluated the antiproliferative activity of CP in leukemia cell lines finding a significant efficacy, especially against SEM and RS4;11 cells." (PMID 24980813, 2014). "Herein we demonstrated that, in RS4;11 and SEM B-leukemia cell lines, CP induced the accumulation of ubiquitinated proteins and ER stress through the inhibition of proteasome system and suppression of protein degradation." (PMID 24980813, 2014). "To evaluate the effect of CP on the proteasome activity in leukemia cells, we tested increasing concentrations of the compound on semipurified 26S proteasome extract from RS4;11 and SEM cells, and measured the functioning of each individual proteolytic activity under cell-free condition." (PMID 24980813, 2014). "In this regard, it should be taken into account that the leukemia cell lines, CEM and THP-1, used in this study may not fully represent the cP vs. iP distribution in primary cells, as in these in vitro models, cP expression is two-fold higher than iP expression." (PMID 33802801, 2021).
mastitis (6 papers, 2015 to 2025). Inflammation of breast tissue during lactation or postpartum due to an obstructed duct or infection. "On a global scale, attention is largely focused on the role of CP as an indicator of mastitis pathology." (PMID 41283399, 2025). "During inflammatory episodes such as mastitis, plasma concentrations of acute phase proteins such as haptoglobin and ceruloplasmin are likely to increase." (PMID 28740504, 2017). "The CP NT had more twins (47 vs 23%, P=0.044) and more mastitis (22 vs 0%, P=0.009) and the PP had more mastitis (16 vs 0%, P=0.017)." (PMID 26658121, 2016). "In the works of Szczubial M. and Saleh N., it was shown that an increase in the level of ceruloplasmin activity in cows’ milk coincides with the manifestations of both clinical mastitis (of varying severity) and subclinical mastitis, which was noted in the work of Sadat A.." (PMID 41283399, 2025). "In particular, our study confirmed the high prevalence of non-encapsulated S. aureus strains derived from bovine mastitis, which underscores the importance of losing CP expression to be expected a key S. aureus feature associated with persistence." (PMID 27790200, 2016).
neuroferritinopathy (6 papers, 2012 to 2025). Neuroferritinopathy is a late-onset type of neurodegeneration with brain iron accumulation (NBIA) characterized by progressive chorea or dystonia and subtle cognitive deficits. "Two other genes also cause NBIA, acoeruloplasminaemia due to mutations in the (ceruloplasmin) CP gene and neuroferritinopathy, caused by mutations in the FTL (ferritin light polypeptide) gene." (PMID 20619503, 2012).
periodontitis (6 papers, 2015 to 2023). An acute or chronic inflammatory process that affects the tissues that surround and support the teeth. "In the subgroup analyses, there was not a significant association between MMP-2 -753C>T polymorphism and periodontitis risk under all five genetic models in the CP and AgP groups." (PMID 31497543, 2019). "Periodontitis showed an increase in ceruloplasmin gene expression in polymorphonuclears in comparison with controls." (PMID 36233348, 2022). "A study by Harshavardhana et al12 showed an increase in serum levels of ceruloplasmin in both chronic and aggressive periodontitis, with greater changes in patients with aggressive periodontitis." (PMID 27651883, 2016). "In other studies lower salivary glutathione—the main intracellular antioxidant and ceruloplasmin—an important extracellular antioxidant were reported in periodontitis patients in comparison to healthy probands." (PMID 26539412, 2015). "In the present study, the relative abundance of Pseudomonas in the CP-OLP group was increased than that of the CP group, which indicated that OLP may increase susceptibility to opportunistic infections in periodontitis patients and enhance inflammation in the periodontium." (PMID 34258290, 2021).
rheumatoid arthritis (6 papers, 2013 to 2026). A chronic, systemic autoimmune disorder characterized by inflammation in the synovial membranes and articular surfaces. "In various studies, elevated ceruloplasmin expression has been associated with various inflammatory diseases, including ankylosing spondylitis, rheumatoid arthritis, and Behçet’s disease." (PMID 41402737, 2025). "Research indicates that the progression of OA and rheumatoid arthritis (RA) is associated with elevated levels of Cu and CP." (PMID 39329090, 2024). "Analysis of the synovial fluid of patients with rheumatoid arthritis revealed that CP is proteolytically degraded to a variable extent during this inflammatory process." (PMID 29329239, 2018). "Additionally, an elevated level of ceruloplasmin has been closely correlated with some auto-immune diseases, such as rheumatoid arthritis and systemic lupus erythematous." (PMID 23505556, 2013). "Moreover, Mito-CP can be evaluated for its suppression of EBV reactivation, which is associated with pathologies (such as infectious mononucleosis) and autoimmune diseases (such as rheumatoid arthritis and multiple sclerosis) and translated clinically in combination with other antiviral drugs." (PMID 28426671, 2017).
acute liver failure (5 papers, 2022 to 2025). Rapid deterioration of liver function causing encephalopathy and coagulopathy. "In WD patients with acute liver failure, serum ceruloplasmin levels <0.2 g/L by nephelometry provided a diagnostic sensitivity of 56% and specificity of 63%." (PMID 36570465, 2022). "However, it has been reported that in patients with acute liver failure, a serum CP cut-off of 20 mg/dL provided only 21% diagnostic sensitivity and 84% specificity for WND." (PMID 37296680, 2023). "A total of 13 WD patients had serum ceruloplasmin between 15 and 20 mg/dL, 3 of whom presented with acute liver failure and 10 were asymptomatic." (PMID 35296237, 2022). "For the patients with acute liver failure, the mean level of serum ceruloplasmin in WD patients (9.3 ± 4.7 mg/dL) was lower than that in non-WD patients (29.7 ± 14.3 mg/dL) (p < 0.001)." (PMID 35296237, 2022). "When considering the diagnosis of WD in the setting of acute liver failure, the interpretation of conventional copper testing is often misleading, as serum copper is high, 24 h urinary copper excretion very high, and ceruloplasmin levels can be either low, normal, or high." (PMID 36673066, 2023). "Of 15 WD children with acute liver failure, serum ceruloplasmin was significantly higher and the age at diagnosis was much older while compared with 302 WD children without acute liver failure (p < 0.01, p < 0.001)." (PMID 35296237, 2022). "Another 13 WD patients in our study had serum ceruloplasmin between 15 and 20 mg/dL, 3 of whom presented with acute liver failure, indicating serum ceruloplasmin is not a sensitive biomarker for WD in the situation of acute liver failure." (PMID 35296237, 2022). "None of WD patients with acute liver failure had serum ceruloplasmin level > 20 mg/dL." (PMID 35296237, 2022).
amyotrophic lateral sclerosis (5 papers, 2020 to 2025). Amyotrophic lateral sclerosis (ALS) is a neurodegenerative disease characterized by progressive muscular paralysis reflecting degeneration of motor neurons in the primary motor cortex, corticospinal tracts, brainstem and spinal cord. "Furthermore, defective RNA editing of GluA2 can cause altered expression of CP‐AMPARs and is implicated in motor neuron damage (amyotrophic lateral sclerosis) and the proliferation of cells in malignant gliomas." (PMID 33533533, 2021). "KEGG database annotation analysis revealed that, relative to the CP group, the SP group was significantly enriched in metabolic pathways related to transcription-related proteins, meiosis–yeast, cellular antigens, amyotrophic lateral sclerosis, and synthesis and degradation of ketone bodies." (PMID 40129929, 2025).
Ascites (5 papers, 2020 to 2025). Accumulation of fluid in the peritoneal cavity (between the layers of the peritoneum that lines the abdomen). "A mean baseline MELD score of 10.1 was reported for the CP B group (n = 21), and 95% of these patients (20/21) had clinical features of decompensation (ascites, 81% [17/21]; hepatic encephalopathy, 67% [14/21]; median albumin, 3.2 g/dL)." (PMID 32270053, 2020). "While liver‐related SAEs were rare among patients in the CP A group, several patients in the CP B group experienced liver‐related SAEs, including ascites, hepatic encephalopathy, and de novo HCC." (PMID 32270053, 2020). "In univariate analysis, the presence of ascites, HE, alanine aminotransferase (ALT) levels, creatinine levels, CP class at 12 weeks after the EOT and MELD score at 12 weeks after the EOT were significant factors." (PMID 37831182, 2023). "In human medicine, C-reactive protein (CRP) measured in both serum and pleural effusion, SAA in pleural and peritoneal effusion, and AGP and ceruloplasmin in pleural effusion have all been shown to discriminate between exudates and transudates." (PMID 37370428, 2023). "They had a more advanced disease as documented by more frequent presence of encephalopathy and ascites, as well as higher levels of bilirubin, lower serum albumin and PT-INR prolongation, resulting in higher CP and Model for End-stage Liver Disease (MELD) scores." (PMID 40392481, 2025).
autism (5 papers, 2015 to 2023). Persistent deficits in social interaction and communication and interaction as well as a markedly restricted repertoire of activity and interest as well as repetitive patterns of behavior. "Although 38 children with a severe form of infantile autism (3.6–18 y) had a Zn level in a normal range, the Cu and CP levels were significantly higher." (PMID 36677007, 2023). "Compared to the controls, the autism group showed a significant increase in oxidative DNA damage in lymphocytes, plasma CP and Cu levels with a high Cu/Zn ratio, thiol proteins, and SOD activity." (PMID 36677007, 2023). "Compared to controls, the autism group showed a significant increase in oxidative DNA damage in lymphocytes, plasma ceruloplasmin and copper levels with a high copper/zinc ratio, thiol proteins, and superoxide dismutase (SOD) activity." (PMID 33294225, 2020). "Contrarily, the serum levels of major antioxidant proteins, transferrin (iron-binding protein) and ceruloplasmin (copper-binding protein), were found to be significantly decreased in children with autism compared to their non-autistic siblings." (PMID 25769033, 2015).
bile duct cancer (5 papers, 2017 to 2025). "Given that the expression of Ceruloplasmin is associated with advanced T stage and perineural invasion, it is a potential prognostic marker for bile duct cancer." (PMID 34907282, 2021). "Ceruloplasmin is supposed to be related with advanced T stage and perineural invasion, having a possibility as a candidate prognostic marker for bile duct cancer." (PMID 28423673, 2017). "In lung, colon, ovarian, and bile duct cancers, C5a production does not appear to be associated with the activation of the CP or AP, a matter that still needs to be clarified." (PMID 40370471, 2025). "Certain types of cancer cells, such as those found in lung, colon, ovarian, and bile duct cancers, secrete C5a into the TME, independently of CP and AP, initiating an autocrine loop that enhances cell proliferation and fosters metastasis." (PMID 40370471, 2025).
cholestasis (5 papers, 2005 to 2025). Impairment of the bile flow caused by obstruction within the liver, or outside the liver in the bile duct system. "In this study, we observed strong expression of ceruloplasmin in extrahepatic bile duct cancer with advanced T stage and perineural invasion, suggesting a correlation with the severity of bile duct obstruction." (PMID 28423673, 2017). "These patients were more frequently female (46% vs. 27%; p = 0.001), less frequently associated with HIV as risk factor for PSVD diagnosis (2% vs. 16%; p = 0.018), yielded higher ceruloplasmin levels (30 ± 8 vs. 26 ± 7 mg/dL; p = 0.014) as well as higher cholestasis parameters." (PMID 39807082, 2025). "Collectively, these findings indicate that cholestasis and hypercholesterolemia induced by BDL are ameliorated by CP-MSC transplantation." (PMID 29250120, 2017).
coronary heart disease (5 papers, 2020 to 2023). "Most of the studies confirm a direct link between elevated ceruloplasmin levels and the frequency of coronary heart disease." (PMID 36361589, 2022). "Nevertheless, in our case-control study, we revealed a decrease in the level of some isoforms of ceruloplasmin in patients with coronary artery disease and coronary atherosclerosis." (PMID 36361589, 2022). "Most of 18 eligible studies reviewed support a direct relationship between ceruloplasmin elevated levels and incidence of coronary heart disease." (PMID 33096845, 2020). "Our results highlight the importance of promoting clinical trials that determine the functions of ceruloplasmin as a mediator in the development of coronary heart disease and evaluate whether the treatment of elevated ceruloplasmin levels has a role in the prognosis or prevention of this condition." (PMID 33096845, 2020). "In patients with coronary heart disease (CHD), there is a decrease in the level of ceruloplasmin." (PMID 33033454, 2020).
diabetic retinopathy (5 papers, 2013 to 2025). "Of the differentially expressed proteins, we were particularly interested in APOA2 and CP, which play critical roles in lipoprotein metabolism, inflammation, oxidative stress, apoptosis, and other processes associated closely with the development of diabetic retinopathy." (PMID 29850212, 2018). "Particularly, the dysregulation of CP expression by Müller cells has been reported for various retinal diseases, including AMD, diabetic retinopathy, and retinal detachment." (PMID 40650085, 2025).
iron deficiency (5 papers, 2015 to 2025). "Because iron requires ceruloplasmin for oxidation and binding to transferrin (and total body stores of copper directly influence ceruloplasmin production), low serum copper levels are typically associated with microcytic anemia due to iron deficiency." (PMID 34434682, 2021). "Ceruloplasmin is essential for iron homeostasis by favoring cellular iron release and has been described to decrease upon iron deficiency." (PMID 26106459, 2015). "The iron-related biomarkers indicated a pattern of iron deficiency, including in non-anemic patients, with reduced % transferrin saturation (p < 0.01) and an elevated ceruloplasmin/transferrin ratio (p = 0.02)." (PMID 40507970, 2025). "A recent study demonstrated that iron deficiency without anemia is associated with decreased levels of blood copper and ceruloplasmin and reduced superoxide dismutase activity in erythrocytes while iron deficiency has been associated with biomarkers of oxidative stress." (PMID 35203218, 2022).